BMI1 (BMI1 proto-oncogene, polycomb ring finger)
Diseases named in the same sentence as BMI1 in open-access papers (continued):
Sharing a sentence is not in itself a finding about the gene and the disease.
ovarian carcinoma (61 papers, 2010 to 2025). A malignant neoplasm originating from the surface ovarian epithelium. "Increased ROR1 expression resulted in elevated RhoA, YAP/TAZ, and BMI-1 levels in a panel of OC cell lines as well as primary ovarian cancer patient-derived cells, underlining the translational relevance of our studies." (PMID 32989221, 2020). "The importance of BMI1 is further underscored by the fact that it has been implicated in several different malignancies including ovarian cancer leading to the development of clinical small molecule inhibitors." (PMID 28270146, 2017). "This is the first study evaluating the expression of Bmi-1 by IHC, in association with clinicopathological and prognostic significance for a large number of ovarian cancer patients." (PMID 20377880, 2010). "In univariate survival analysis of the ovarian carcinoma cohorts, a significant association of intensive expression of Bmi-1 with shortened patient survival (mean 49.3 months versus 100.3 months, p < 0.001) was demonstrated." (PMID 20377880, 2010). "In ovarian carcinomas, significant positive associations were found between intensive expression of Bmi-1 and the tumors ascending histological grade, later pT/pN/pM and FIGO stages (P < 0.05)." (PMID 20377880, 2010). "The association between Bmi-1 expression in ovarian carcinomas and several known clinico-pathological features was further studied." (PMID 20377880, 2010). "Previous studies have demonstrated that BMI1 promotes TCs growth and metastasis in ovarian cancer by altering TCs angiogenesis and extracellular matrix structure, primarily through the regulation of adhesion plaques and the PI3K/AKT signaling pathway." (PMID 40612060, 2025). "miR-15a and miR-16 directly target the 3'-UTR of Bmi-1 (a component of Polycomb complexes), and their expression levels are significantly correlated with the Bmi-1 protein level in ovarian cancer." (PMID 38539161, 2024). "Remarkably, one study supports our results, proving that overexpression of BMI1 in ovarian cancer promotes metastasis, decelerates apoptosis, and desensitizes tumor cells to platinum treatment." (PMID 39456618, 2024). "In ovarian cancer, overexpression of various protein signaling effectors of the Hh pathway also induced Bmi-1 expression." (PMID 36726797, 2023). "Our study not only found upregulated PFKFB3 in CSC-enriched ovarian cancer cells, but also revealed that PFKFB3 promoted clonogenicity and sphere-formation, and induced KLF4 and BMI1 expression in ovarian cancer cells." (PMID 35155224, 2022). "A significant albeit very weak correlation was detected between high expression of PFKFB3 and upregulation of KLF4 and BMI1, suggesting KLF4 and BMI1 as the potential downstream targets of PFKFB3 on CSC properties in ovarian cancer." (PMID 35155224, 2022). "Bmi-1 can also activate the PI3K/mTOR/4EBP1 signaling pathway in ovarian cancer cells to regulate cell proliferation." (PMID 35897796, 2022). "In ovarian cancer cells, inhibition of BMI1 gene can induce activation of RIPK1-RIPK3 complex, which phosphorylates its downstream substrate MLKL and enhances necrosis." (PMID 33927214, 2021). "Another study, based on human specimens and ovarian cancer cells, showed that BMI-1 expression is downregulated by MiR-15a or MiR-16 underexpression, with subsequent significant decreases in cell proliferation and clonal growth." (PMID 34199929, 2021). "The experiments conducted in the 3D spheroids model in fact proved that RV synergized with OxPt to induce BAX-mediated cell death in ovarian cancer cells in which BMI-1 was downregulated and LC3 was upregulated." (PMID 34831435, 2021). "Taken together, these data indicate that RV-induced BMI-1 downregulation leading to upregulation of autophagy sensitizes ovarian cancer cells to platinum therapy." (PMID 34831435, 2021). "Bmi-1 overexpression in ovarian cancer is reportedly strongly correlated with histological grade and clinical stage." (PMID 32059385, 2020).
ovarian carcinoma (continued). "The BMI-1 inhibitor PTC-028 in ovarian cancer induced the hyperphosphorylation of BMI-1 and impacted BMI-1 function." (PMID 31640758, 2019). "Bmi-1 activation plays a relevant role in the biology of ovarian cancers, as well as of other numerous solid tumors." (PMID 29389895, 2018). "Bmi-1 protein levels are significantly downregulated in response to miR-15a or miR-16 expression and lead to significant reduction of ovarian cancer cell proliferation and clonal growth." (PMID 29389895, 2018). "In ovarian cancer, BMI1 is regulated by miR-15a and miR-16-1 and induced expression of these miRNAs decreases BMI1 protein levels, reducing ovarian cancer cell proliferation." (PMID 29401683, 2018). "MiR-15a and miR-16 are underexpressed in HGS-OvCa; these miRNAs target the Bmi-1 3′ untranslated region and significantly correlate with Bmi-1 protein levels in primary ovarian cancer tumor specimens." (PMID 29389895, 2018). "In our previous study, we also found significant over-expression of BMI1 in metastatic lymph nodes and recurrent tumors compared to primary ovarian carcinomas." (PMID 29685168, 2018). "In ovarian cancer cell lines, expression of CK2α correlated with the phospho-species, as well as basal BMI1 levels." (PMID 28270146, 2017). "Taken together, our findings establish an important regulatory role of CK2α on BMI1 phosphorylation and stability and implicate the CK2α/BMI1 axis in ovarian cancer." (PMID 28270146, 2017). "Based on these results we posited that if CK2α mediated BMI1 phosphorylation led to protein stability, then a correlation between CK2α and BMI1 protein levels would be expected in ovarian cancer clinical specimens." (PMID 28270146, 2017). "Other mechanisms of BMI1 stability include direct association with the FAL1 long noncoding RNA resulting in increased clonogenicity and tumorigenicity in an ovarian cancer model." (PMID 28270146, 2017). "Our results, generally, demonstrate a correlation between expression of CK2α and phosphorylated BMI1 in ovarian cancer cell lines and patient tissues." (PMID 28270146, 2017). "It has been reported that miR-15a inhibits cell proliferation in pancreatic ductal adenocarcinoma and ovarian cancer by downregulating Bmi-1 expression." (PMID 26894855, 2016). "In ovarian cancer, Bmi-1 protein expression has been shown to be regulated by miR-16 and result in ovarian cancer cell proliferation and tumor growth." (PMID 26655091, 2016). "In ovarian carcinoma, BMI1 expression correlates with histologic grade and disease stage and is associated with resistance to chemotherapeutic agents such as cisplatin." (PMID 26992233, 2016). "Ovarian CSCs are more resistant to cisplatin and paclitaxel when BMI1 is overexpressed, and targeting BMI1 sensitizes ovarian cancer cells to cisplatin." (PMID 27225481, 2016). "In agreement with our results, the increased expression level of BMI1 has been shown to promote the proliferation of ovarian cancer cells." (PMID 25999024, 2015). "In ovarian cancer, the miR-15a and miR-16-1 levels were found to be inversely correlated to the protein expression levels of Bmi-1 which its 3′UTR is the direct target of these miRNAs." (PMID 25743273, 2015). "This study identified BMI1 as an ideal molecule to be targeted to overcome the chemoresistance of CaP cells and corroborates to earlier report showing the utility of BMI1 as a target to overcome chemoresistance in ovarian cancer cells." (PMID 23671559, 2013). "The authors showed that the miR-16 target protein responsible for the proliferative effect in ovarian cancer was the oncogenic protein Bmi-1." (PMID 22583478, 2012). "Amplification of Bmi1 has been seen in 11% of mantle cell lymphomas and chromosomal gains have been seen in high-grade astrocytomas and ovarian cancer." (PMID 22574128, 2012). "Here we demonstrate that Bmi-1 plays an important role insensitization of chemoresistant ovarian cancer cells to cisplatin." (PMID 21445297, 2011).
ovarian carcinoma (continued). "We also establish Bmi-1 as a valid therapeutic targetin vivo using a readily translatable approach of nanoliposomaldelivery of siRNA into an orthotopic mouse model of ovarian cancer." (PMID 21445297, 2011). "To further investigate the mechanism of ROS mediated enhanced apoptosis bycisplatin in Bmi-1 silenced ovarian cancer cells we wanted to test theinvolvement of the DNA damage and repair (DDR) pathway." (PMID 21445297, 2011). "Collectively these findings establish Bmi-1 as animportant new target for therapy in chemoresistant ovarian cancer." (PMID 21445297, 2011). "We performed quantitative RT-PCR todetermine the gene expression level of glutamate-cysteine ligase (GCLM) andglutathione synthase (GSS), in the Bmi-1 siRNA transfected ovarian cancer celllines." (PMID 21445297, 2011). "Overexpression of Bmi1 is frequently observed in various types of human cancers, including lung cancer, ovarian cancer, acute myeloid leukemia, nasopharyngeal carcinoma, and neuroblastoma." (PMID 22194680, 2011). "We next proceeded to determine thetherapeutic efficacy of silencing Bmi-1 in an orthotopic chemoresistant mousemodel of ovarian cancer." (PMID 21445297, 2011). "In an in vivo orthotopic mouse model ofchemoresistant ovarian cancer, knockdown of Bmi-1 by nanoliposomal deliverysignificantly inhibits tumor growth." (PMID 21445297, 2011). "Bmi-1 is frequentlyupregulated in a variety of cancers including ovarian cancer and its correlationwith clinical grade/stage, lymph node metastasis and poor prognosis has beenreported." (PMID 21445297, 2011). "The clinico-pathological and prognostic significance of expression of Bmi-1 in our ovarian carcinoma cohorts was also assessed." (PMID 20377880, 2010). "According to this definition, the intensive expression of Bmi-1 was detected in 67/179 (37%) ovarian carcinomas." (PMID 20377880, 2010). "The methods of immunohistochemistry and fluorescence in situ hybridization were utilized to examine protein expression and amplification of Bmi-1 in 30 normal ovaries, 30 ovarian cystadenomas, 40 borderline ovarian tumors and 179 ovarian carcinomas." (PMID 20377880, 2010). "In our 96 informative cases of ovarian carcinomas by both IHC and FISH simultaneously, intensive expression of Bmi-1 was detected in all (8/8) ovarian carcinomas that had Bmi-1 amplification." (PMID 20377880, 2010). "Clearly, further work needs to be done to more precisely understand the molecular mechanism of Bmi-1 in the development and progression of ovarian carcinoma, as well as other human cancers." (PMID 20377880, 2010). "With regard to the mechanism of up-regulated protein expression of Bmi-1 in ovarian carcinomas, it is known that gene amplification is a common pathological mechanism of gene overexpression in human cancers." (PMID 20377880, 2010). "In ovarian cancer, suppression of Bmi-1 induces autophagy through ATP depletion." (PMID 38141761, 2024). "Knockdown of Bmi-1 induced autophagy in ovarian cancer cells via ATP depletion." (PMID 35897796, 2022). "BMI-1 is a polycomb ring finger transcription factor required for Hedgehog-promoted proliferation, metastasis and chemoresistance, and it correlates with poor prognoses in patients with ovarian cancer." (PMID 34831435, 2021). "Similar observations have been made in ovarian cancer, in which the synthetic glucocorticoid dexamethasone induced ROR1 expression, which correlated with elevated RHOA, YAP/TAZ, and BMI-1 levels in a panel of ovarian cancer cell lines as well as in the primary patient-derived cells." (PMID 33445713, 2021). "Notably, patients bearing low expression of BMI1 exhibited a significantly better overall survival (p = 5.6 ȕ 10−5) than those with high BMI1 expression, indicating that this gene has a relevant prognostic value for the outcomes of ovarian cancer patients." (PMID 34831435, 2021).
ovarian carcinoma (continued). "Finally, we prove that inhibition of BMI-1/Hh pathway along with stimulation of autophagy impairs the growth and sensitizes to platinum ovarian cancer cells." (PMID 34831435, 2021). "For example, lncRNA FAL1 amplified in ovarian cancers could promote cell proliferation by recruiting the chromatin repressor protein BMI‐1 and inhibiting the expression of CDKN1A." (PMID 30216655, 2018). "Interestingly, in chemoresistant ovarian cancer cells, it has been demonstrated that BMI-1 expression regulates GSH production." (PMID 30213983, 2018). "LncRNA FAL1 was amplified in more than 30% of ovarian cancers, which could promote cell proliferation by recruiting the chromatin repressor protein BMI‐1 and inhibiting the expression of CDKN1A." (PMID 30216655, 2018). "B-cell-specific Moloney murine leukemia virus integration site 1 (BMI1) might be an appropriate biomarker in the management of epithelial ovarian cancer (EOC)." (PMID 29685168, 2018). "Interestingly previous reports suggest that expression of both CK2α and BMI1 is elevated in ovarian cancer and correlates with poor overall survival." (PMID 28270146, 2017). "Also, ovarian cancer cells that expressed CK2α but minimally activated AKT maintained phosphorylated species of BMI1." (PMID 28270146, 2017). "Notably, expression of both CK2α and BMI1 is elevated in ovarian cancer and correlates with poor overall survival." (PMID 28270146, 2017). "This suggests that in ovarian cancer cells additional kinases might be involved in phosphorylating BMI1." (PMID 28270146, 2017). "Our results implicate the CK2α/BMI1 axis in ovarian cancer, thus targeting it might be potentially beneficial." (PMID 28270146, 2017). "In addition, it was shown that in ovarian carcinoma cell lines and tissue samples, miR-15a and miR-16 levels were inversely correlated with BMI1 expression." (PMID 26992233, 2016). "Interestingly, BMI1 is a direct target of miR-15a and miR-16, both being frequently down-regulated in ovarian cancer." (PMID 26992233, 2016). "Bhattacharya and colleagues observed the reduced expression of miR-15a and miR-16 in ovarian cell lines and in primary ovarian tissues and found that these miRNAs could inhibit ovarian cancer cell proliferation and clonal growth by targeting Bmi-1." (PMID 25435873, 2014). "In addition, the major transcription factors nuclear factor kappa B1 and BMI1 polycomb ring finger oncogene (BMI1) are overexpressed in ovarian cancer through aberrant downregulation of miR-9, miR-15a, and miR-16." (PMID 24551595, 2014). "Therefore,Bmi-1 or scrambled-control siRNA transfected ovarian cancer cells werepre-treated with N-Acetyl Cysteine (NAC) at 1 mg/ml for 1 h followed bycisplatin treatment for 48 h." (PMID 21445297, 2011). "Thus, Bmi-1 is an important new target fortherapy not only in chemoresistant ovarian cancer but also for other malignanciescharacterized by overexpression of Bmi-1." (PMID 21445297, 2011). "Hence, to determine howsilencing of Bmi-1 sensitizes drug-resistant ovarian cancer cells to cisplatininduced apoptosis, we investigated the possible involvement of ROS." (PMID 21445297, 2011). "In addition,isolated ovarian cancer stem cells exhibit much higher Bmi-1 levels compared to thedifferentiated or parental bulk tumor cells and have increased resistance tocisplatin and paclitaxel when compared to the tumor cells." (PMID 21445297, 2011). "We have previously shown that reduction of Bmi-1 protein levels in ovarian cancercells using microRNA 15a/16 decreases clonal growth and proliferation.Here, we wanted to test if knockdown of Bmi-1 affected cisplatin mediatedapoptosis in ovarian cancer cells." (PMID 21445297, 2011). "In addition, our study introduces Bmi-1 expression as a new independent prognostic marker in ovarian carcinoma with intensive expression of Bmi-1 protein in tumor cells predicting poor outcome of the disease for the individual patient." (PMID 20377880, 2010).
ovarian carcinoma (continued). "It has been suggested that the B-cell specific moloney leukemia virus insertion site 1 (Bmi-1) gene plays an oncogenic role in several types of human cancer, but the status of Bmi-1 amplification and expression in ovarian cancer and its clinical/prognostic significance are unclear." (PMID 20377880, 2010). "Bmi-1 expression could be evaluated informatively in TMA tissues of 163/179 of ovarian carcinomas, 37/40 of borderline tumors and 26/30 of cystadenomas." (PMID 20377880, 2010). "Our results provide a basis for the concept that increased expression of Bmi-1 in human ovarian carcinoma may be important in the acquisition of an invasive and/or aggressive phenotype." (PMID 20377880, 2010). "In addition, we found that the frequency of intensive expression of Bmi-1 in undifferentiated ovarian carcinomas was significantly larger than that in other types of carcinoma." (PMID 20377880, 2010). "However, to our best knowledge, there is little information about prognostic status and clinical outcome of Bmi-1 expression in ovarian cancer." (PMID 20377880, 2010). "Furthermore, intensive expression of Bmi-1 in our ovarian carcinoma cohorts was strongly correlated with an ascending histological grade and clinical stage (pT/pN/pM and FIGO stage) of the tumor." (PMID 20377880, 2010). "Amplification of Bmi-1 was detected in 8% of ovarian carcinomas." (PMID 20377880, 2010). "In an ovarian cancer model, the Bmi-1 inhibitor PTC028 was shown to selectively inhibit cancer cell growth while leaving normal cells unaffected, which could present a unique benefit as compared to conventional chemotherapeutic agents that do not selectively eliminate tumor cells." (PMID 36726797, 2023). "Finally, we addressed whether the LPA-promoted signature associated with Hh (GLI1, BMI1) and EMT (SNAI1, TWIST1) genes has an impact on the clinical outcome of ovarian cancer patients." (PMID 34831435, 2021). "We find that re-expression of phosphorylatable but not non-phosphorylatable BMI1 rescues clonal growth in endogenous BMI1 silenced ovarian cancer cells leading us to speculate that CK2α-mediated phosphorylation stabilizes BMI1 and promotes its oncogenic function." (PMID 28270146, 2017). "Moreover, BMI-1 silencing enhanced cisplatin-therapy response in ovarian cancer." (PMID 28968963, 2017). "Therefore, the oncogenic roles of both EZH2 and BMI1 and the implication of the lncRNAs/Polycomb axis with miRNAs show that lncRNAs and their functional protein partners are highly involved in the biology of ovarian cancer cells." (PMID 26992233, 2016). "Therefore we demonstrate thatsilencing of Bmi-1 in ovarian cancer cells whether in vitro orin vivo increases apoptosis in response to cisplatin." (PMID 21445297, 2011). "In both the cell lines,knockdown of Bmi-1 followed by any cisplatin treatment significantly increasedROS generation.These data corroborate our previous observations on apoptosis and posits ROS asthe primary reason for enhanced sensitization of ovarian cancer cells tocisplatin." (PMID 21445297, 2011). "Since it was suggested that modulation of Bmi-1 protein might be involved in human colorectal carcinogenesis by repressing p16Ink4a/p14ARF proteins {14}, we further examined the expression of p16Ink4a/p14ARF by IHC in our ovarian carcinoma cohorts." (PMID 20377880, 2010). "Recently, in primary ovarian carcinoma culture, VEGFA had been shown to promote tumor-initiating cells through Src-DNMT3A-driven miR-128-2 methylation and Bmi1 upregulation." (PMID 35884426, 2022). "This conclusion was based on observations in ovarian cancer stem cells, in which ROR1 was highly expressed and regulated the expression of the self-renewal marker polycomb complex protein BMI-1." (PMID 33445713, 2021). "Overall, DHA targets the miR-200b–BMI-1/VEGF-A axis to suppress cancer stemness and metastatic potential, highlighting its therapeutic promise in overcoming the limitations of standard chemotherapy for ovarian cancer." (PMID 41345229, 2025).